ZNF43 (zinc finger protein 43)
Description:
May be involved in transcriptional regulation.
Synonyms: KOX27; ZNF39L1; HTF6
Tractability: PROTAC: ubiquitination databases record sites on it.
Gene: Protein-coding gene on chromosome 19 (21,804,946 to 21,852,125, reverse strand). Ensembl gene ENSG00000198521.
Subcellular location: Nucleus
Pathways (Reactome):
Gene expression (Transcription): Generic Transcription Pathway
Gene Ontology:
Molecular function: DNA binding; transcription cis-regulatory region binding
Biological process: regulation of transcription by RNA polymerase II; regulation of DNA-templated transcription
Cellular component: nucleus
Genetic constraint (gnomAD): Loss-of-function variants: 44 observed, 67.56 expected, observed/expected ratio (o/e) 0.65, 90% interval 0.51 to 0.84. The upper end of that interval is the gene's LOEUF score, 0.84, which puts it in group 3 of 6, group 1 being the genes least tolerant of losing a copy. Missense variants: 896 observed, 941 expected, observed/expected ratio (o/e) 0.95, 90% interval 0.9 to 1.01. Synonymous variants: 308 observed, 311.11 expected, observed/expected ratio (o/e) 0.99, 90% interval 0.9 to 1.09.
Homologues: Orthologues: chimpanzee ZNF43 (99% identical), macaque ZNF43 (95% identical). Paralogues in human: ZNF724 (56% identical), ZNF681 (53% identical), ZNF254 (52% identical), ZNF429 (51% identical), ZNF726 (51% identical), ZNF708 (50% identical), ZNF85 (50% identical), ZNF728 (49% identical), ZNF493 (47% identical), ZNF93 (46% identical), ZNF676 (46% identical), ZNF90 (42% identical), and 164 more.
Diseases named in the same sentence as ZNF43 in open-access papers:
ZNF43 is named in the same sentence as 14 diseases in open-access papers, as found by Europe PMC text mining. Sharing a sentence is not in itself a finding about the gene and the disease. The quoted sentences say what the papers report.
colorectal cancer (2 papers, 2022). A primary or metastatic malignant neoplasm that affects the colon or rectum. "Hypermethylated ZNF43 has been reported as a biomarker for colorectal cancer." (PMID 35313869, 2022).
colon cancer (1 paper, 2023). "The most specific loci were in the exons of genes JAK1 and CHD3 (for endometrial cancer); BMPR2, ELAV3, GLYR1, and ZNF43 (for colon cancer); and XYLT2 (for stomach cancer)." (PMID 37894432, 2023).
hepatocellular carcinoma (1 paper, 2022). A malignant tumor that arises from hepatocytes. "Besides, DRD4, ZNF132 and ZNF43 have been linked with other non-lung cancer types: DRD4, encoding dopamine receptor, is involved in early brain development and epigenetically repressed in pediatric CNS tumors; it also has be identified as a potential epidriver in hepatocellular carcinoma." (PMID 35313869, 2022).
neuroblastoma (1 paper, 2023). Neuroblastoma (NB) is the most common solid, extracranial childhood tumor. "On the contrary, neuroblastoma patients with age at diagnosis < 18months and with ZNF43 higher expressions had the best prognosis in E-MTAB-1781 and TARGET datasets." (PMID 37904225, 2023). "Neuroblastoma patients with age at diagnosis < 18months and with ZNF43 higher expressions had the medium clinical survival in E-MTAB-1781, TARGET and GSE62564 datasets." (PMID 37904225, 2023).
cancer (3 papers, 2021 to 2022). A tumor composed of atypical neoplastic, often pleomorphic cells that invade other tissues. "Besides, methylation of DRD4, ZNF132 and ZNF43 have been reported to play roles in other cancer types." (PMID 35313869, 2022). "The patients with ZNF43-methylated normal tissue were at earlier cancer stages than those without ZNF43-methylated tissue." (PMID 36142151, 2022).
Tumor (3 papers, 2007 to 2024). "To analyze the patterns of gene methylation in patients with CRC, we evaluated the methylation levels of PTGER4 and ZNF43 in both tumor tissue and adjacent normal tissue." (PMID 36142151, 2022). "C5orf4 has been identified as a putative tumour suppressor, whilst ZNF43 has been shown, in vitro, using Ewing Sarcoma derived EW-1 cells, to be highly expressed in proliferating cells and down regulated in cells induced to differentiate." (PMID 17663764, 2007). "In this study, both PTGER4 and ZNF43 were classified as tumor-suppressor genes." (PMID 36142151, 2022). "Zinc finger protein 43 (ZNF43) is known to be involved in transcriptional regulation and is classified as a tumor-suppressor gene." (PMID 38287071, 2024). "Tumor tissue and matched adjacent nontumorous tissue were extracted from 208 patients with CRC, and the correlation between the methylation levels of PTGER4 and ZNF43 at certain CpG loci and the prognostic factors of CRC was determined using the MassARRAY System testing platform." (PMID 36142151, 2022).
ZNF43 also shares sentences with these, for which no sentence is quoted: adenoma (1 paper); CNS tumors (1); dysplasia (1); endometrial cancer (1); gastrointestinal stromal tumor (1); lung carcinoma (1); stomach cancer (1); thymoma (1).